RNU6-168P (RNA, U6 small nuclear 168, pseudogene)
Gene: Small nuclear RNA gene on chromosome 5 (163,796,065 to 163,796,165, reverse strand). Ensembl gene ENSG00000251998.
Homologues: Orthologues: chimpanzee U6 (100% identical), guinea pig U6 (68% identical), mouse Gm25332 (67% identical), rabbit U6 (67% identical), rat LOC120099431 (67% identical), pig U6 (60% identical). Paralogues in human: RNU6-648P (80% identical), RNU6-931P (80% identical), RNU6-1091P (79% identical), RNU6-1094P (79% identical), RNU6-1209P (79% identical), RNU6-1287P (79% identical), RNU6-1316P (79% identical), RNU6-20P (79% identical), RNU6-214P (79% identical), RNU6-216P (79% identical), RNU6-35P (79% identical), RNU6-797P (79% identical), and 1285 more.